SPECC1L (sperm antigen with calponin homology and coiled-coil domains 1 like)
Description:
Involved in cytokinesis and spindle organization. May play a role in actin cytoskeleton organization and microtubule stabilization and hence required for proper cell adhesion and migration.
Synonyms: CYTSA; KIAA0376; GBBB2; OBLFC1; TBHS; TBHS1
Tractability: PROTAC: ubiquitination databases record sites on it; its protein half-life has been measured.
Gene: Protein-coding gene on chromosome 22 (24,270,817 to 24,417,740, forward strand). Ensembl gene ENSG00000100014.
Subcellular location: Cytoplasm, cytoskeleton; Cytoplasm, cytoskeleton, spindle; Cell junction, gap junction
Subcellular location (Human Protein Atlas): Actin filaments
Gene Ontology:
Molecular function: protein binding; beta-catenin binding
Biological process: cell adhesion; actin cytoskeleton organization
Cellular component: actin cytoskeleton; filamentous actin; microtubule organizing center; cell-cell junction; cytoplasm; cytoskeleton; gap junction; microtubule cytoskeleton; spindle
Genetic constraint (gnomAD): Loss-of-function variants: 37 observed, 112.03 expected, observed/expected ratio (o/e) 0.33, 90% interval 0.25 to 0.43. The upper end of that interval is the gene's LOEUF score, 0.43, which puts it in group 1 of 6, group 1 being the genes least tolerant of losing a copy. Missense variants: 1,077 observed, 1,406.2 expected, observed/expected ratio (o/e) 0.77, 90% interval 0.73 to 0.81. Synonymous variants: 493 observed, 517.75 expected, observed/expected ratio (o/e) 0.95, 90% interval 0.88 to 1.03.
Homologues: Orthologues: chimpanzee SPECC1L (99% identical), dog SPECC1L (97% identical), guinea pig SPECC1L (97% identical), rabbit SPECC1L (96% identical), mouse Specc1l (95% identical), macaque SPECC1L (95% identical), rat Specc1l (95% identical), pig SPECC1L (93% identical), tropical clawed frog specc1l (75% identical), zebrafish specc1la (70% identical), zebrafish specc1lb (65% identical), Drosophila melanogaster spdi (29% identical). Paralogues in human: SPECC1 (38% identical).
Diseases named in the same sentence as SPECC1L in open-access papers:
SPECC1L is named in the same sentence as 32 diseases in open-access papers, as found by Europe PMC text mining. Sharing a sentence is not in itself a finding about the gene and the disease. The quoted sentences say what the papers report.
orofacial cleft (3 papers, 2016 to 2022). A disorder of facial skeleton that is characterized by cleft lip and/or cleft palate that result in feeding, speech and hearing problems caused by failures during development. "The first pathogenic dominant mutations implicating the SPECC1L gene were reported in patients with oblique facial clefting (ObFC), a rare form of orofacial cleft." (PMID 35205294, 2022). "Mutations in TWIST1 and SPECC1L lead to craniosynostosis and orofacial clefting in humans." (PMID 35781329, 2022). "Thus, heterozygous SPECC1L loss-of-function mutations identified in human patients may lead to mild perturbation in SPECC1L function during craniofacial morphogenesis, sufficient to account for their orofacial clefts." (PMID 26787558, 2016).
acne (2 papers, 2018 to 2021). An inflammatory process of the sebaceous glands which is characterized by comedones, nodules, papules and/or pustules on the skin. "SPECC1L is also reported to be a component of the Wnt signaling pathway and may be implicated in acne development." (PMID 33849530, 2021).
autosomal dominant Opitz G/BBB Syndrome (2 papers, 2016 to 2022). "Here, we report the molecular screening for mutations in the coding and splice site regions of the SPECC1L gene in samples of sporadic patients diagnosed with Opitz G/BBB syndrome who resulted negative for mutations in the MID1 gene responsible for the X-linked form of the disease." (PMID 35205294, 2022).
colorectal cancer (2 papers, 2017 to 2022). A primary or metastatic malignant neoplasm that affects the colon or rectum. "In this study, we report the effects of depleting cytospin-A (CYTSA), also known as the sperm antigen with calponin homology and coiled-coil domain (SPECC1L) protein, on the proliferation and migration of colorectal cancer (CRC) cells." (PMID 35454887, 2022).
hypospadias (2 papers, 2022). Hypospadias is the displacement of the urethral meatus on the ventrum of the penis. "Two patients (patients 1 and 6) carried SALL1 and SPECC1L mutations at the same time, which are involved in syndromes including hypospadias, but the role of these two mutations in the two patients may need to be further studied." (PMID 35669683, 2022). "Our study confirms that patients with diagnosis of OS, mainly characterized by the presence of hypospadias and laryngo–tracheo–esophageal defects, do not carry pathogenic SPECC1L mutations." (PMID 35205294, 2022). "Consistently, our study confirms that patients with diagnosis of OS, mainly characterized by the presence of hypospadias and absence of CDH, do not carry SPECC1L pathogenic missense variants, despite the fact that, in some cases, bioinformatic tools give contrasting significance predictions." (PMID 35205294, 2022).
cervical cancer (1 paper, 2018). A primary or metastatic malignant neoplasm involving the cervix. "Taken together, these results indicated that BAP31 affects the migration and invasiveness of cervical cancer cells by regulating the expression and subcellular localization of the metastasis-related proteins Drebrin, M-RIP, SPECC1L, and Nexilin." (PMID 30022068, 2018). "Moreover, depletion of BAP31 inhibits cervical cancer cell invasion and migration by regulating the expression and subcellular localization of Drebrin, M-RIP, SPECC1L, and Nexilin, and then affect the cytoskeleton assemblage." (PMID 30022068, 2018).
cervical tumors (1 paper, 2018). "In addition, BAP31 can regulate the metastasis of cervical tumors, preferably by modulating the expression and subcellular localization of the metastasis-related proteins Drebrin, M-RIP, SPECC1L, and Nexilin." (PMID 30022068, 2018).
cleft palate (1 paper, 2025). Cleft palate is a fissure type embryopathy that affects the soft and hard palate to varying degrees. "Some subsequent studies observed unilaterally elevated PS in normal embryos, and others that observed unilateral elevation in mutant mouse models of cleft palate, including those with Specc1l deficiency." (PMID 40008102, 2025).
diabetic nephropathy (1 paper, 2023). "Data mining of the published microbial quantitative trait loci indicated that the risk genotypes of rs2294239 (ZNRF3) and rs3747113 (SPECC1L) in diabetic nephropathy were correlated with the abundance of Lactococcus, which is a microorganism that is beneficial to the human body." (PMID 38189041, 2023).
DiGeorge syndrome (1 paper, 2023). "A 22q11.21 microdeletion encompassing the TBX1, SHANK3, SOX10, AP1B1, FBXO7, MYH9, and SPECC1L genes cause DiGeorge syndrome, which is associated with DD, ID, seizure, and cardiac malformations, with a prevalence of 1 in 4000." (PMID 37189911, 2023).
Kawasaki disease (1 paper, 2021). A rare inflammatory disease characterized by an acute febrile, systemic, self-limiting, medium-vessel vasculitis primarily affecting children. "The effect of five SNPs that showed to be the most statistically associated with the Kawasaki disease in this study was evaluated, this includes: rs12037447 in non-coding sequence and rs146732504 in KIF25, rs151078858 in PTPRJ, rs55723436 in SPECC1L, rs6094136 in RPN2 genes." (PMID 33692975, 2021). "The potential linkage between SPECC1L and the immune system or inflammation and Kawasaki disease is unknown." (PMID 33692975, 2021). "We found that five single nucleotide polymorphisms were more commonly found in Polish children with Kawasaki disease than in adults: rs12037447 (non-coding region), rs146732504 (KIF25), rs151078858 (PTRPJ), rs55723436 (SPECC1L), rs6094136 (RNP2)." (PMID 33692975, 2021).
mixed neuronal-glial tumor (1 paper, 2022). A group of central nervous system neoplasms with a variable amount of neuronal and, less consistently, glial differentiation. "Surrey reported a case of mixed neuronal-glial tumors (MNGT) with SPECC1L::NTRK2 fusion." (PMID 36531047, 2022).
non-small cell lung carcinoma (1 paper, 2023). A group of at least three distinct histological types of lung cancer, including non-small cell squamous cell carcinoma, adenocarcinoma, and large cell carcinoma. "The evidence of anaplastic lymphoma kinase (ALK) inhibitor for non-small cell lung cancer (NSCLC) harbouring sperm antigen with calponin homology and coiled-coil domains 1-like (SPECC1L)-ALK fusion was limited." (PMID 38234623, 2023).
ocular coloboma (1 paper, 2020). "In addition, through bioinformatics analysis of the genes mapped to the 22q11.2 region, deregulation of the SPECC1L gene could be implicated in the development of coloboma." (PMID 32807111, 2020). "In addition, through bioinformatics analysis of the genes mapped to the 22q11.2 region, it is proposed that deregulation of the SPECC1L gene could be implicated in the development of ocular coloboma." (PMID 32807111, 2020).
sarcoma (1 paper, 2024). A usually aggressive malignant neoplasm of the soft tissue or bone. "The diagnosis was made after the analysis of a punch biopsy specimen by a bone and soft tissue pathologist as a low-grade sarcoma harboring a sperm antigen with calponin homology and coiled-coil domains 1-like (SPECC1L)-NTRK3 fusion transcript." (PMID 39717285, 2024).
van der Woude syndrome (1 paper, 2019). Van der Woude syndrome (VWS) is a rare congenital genetic dysmorphic syndrome characterized by paramedian lower-lip fistulae, cleft lip with or without cleft palate, or isolated cleft palate. "ALDH3A2 (aldehyde dehydrogenase 3 family member A2), a membrane-associated protein, and SPECC1L are implicated in craniofacial disorders (e.g., Van Der Woude syndrome) in humans." (PMID 30689847, 2019).
tumor (4 papers, 2019 to 2024). "To date, responses to ALKi in two NSCLC patients with different SPECC1L-AL fusion variants have been published only in one previous work, and the clinical outcome of the patients supports the idea that SPECC1L may be a tumor driver factor that can be inhibited by a series of TKIs." (PMID 39063924, 2024). "FISH analysis of tumor cells by using SPECC1L-ALK DNA probes showed a fusion of orange (ALK) and green (SPECC1L) into yellow signals." (PMID 34559836, 2021). "In addition, WTlig tensin 1/3 (TENS1/3; 54 matches; HCC027) and SPECC1L-ADORA (33 matches; HCC028) were detectable in the respective tumor HLA immunoprecipitates, proving that at least the wild-type sequence peptide is processed and presented on HLA." (PMID 31039795, 2019).
cancer (3 papers, 2017 to 2022). A tumor composed of atypical neoplastic, often pleomorphic cells that invade other tissues. "Because the BAP31 protein mainly shuttles between the ER and Golgi, we determined that BAP31 could regulate the expression and subcellular localization of Drebrin, M-RIP, SPECC1L, and Nexilin, which play critical role in actin cytoskeletal remodeling and are involved in cancer metastasis." (PMID 30022068, 2018). "Interestingly, F-actin-binding protein (Drebrin, SPECC1L, and Nexilin) and upstream cytoskeletal modulator (M-RIP) play critical role in actin cytoskeletal remodeling and are involved in cancer metastasis." (PMID 30022068, 2018).
SPECC1L also shares sentences with these, for which no sentence is quoted: Alzheimer disease (2 papers); osteosarcoma (2); adenocarcinoma (1); brain tumors (1); colon cancer (1); colorectal adenocarcinoma (1); craniosynostosis (1); frontonasal dysplasia (1); Laryngeal cleft (1); mesenchymal tumors of (1); metabolic syndrome (1); metastatic tumor (1); nasopharyngeal carcinoma (1); spindle cell tumors (1).